IL6 (interleukin 6)
Diseases named in the same sentence as IL6 in open-access papers (continued):
Sharing a sentence is not in itself a finding about the gene and the disease.
parasitemia (continued). "It is likely, therefore, that the low IL6 levels associated with the CC genotype lead to a lack of immune-mediated protection against parasitemia, while the high IL6 levels observed in GG individuals create a relatively severe inflammatory background that also favors T. cruzi replication." (PMID 33193300, 2020). "Parasitemia assessment, behavioral analysis, levels of proinflammatory cytokines (TNF‐α and IL‐6) in the hippocampus and prefrontal cortex, and levels of the neurotrophin BDNF in the hippocampus." (PMID 41093288, 2026). "This was attributed to the activation of the inflammatory cascade induced by parasitic infection, and TNF-α stimulated the production of inflammatory cytokines (IL-3, IL-6, and IL-10)." (PMID 40007749, 2025). "There was a trend towards a decrease in temperature and the levels of the top five most upregulated cytokines during the participant’s second exposure to high parasitemia, IL-10, CXCL10, IL-1RA, IFNγ, IL-6." (PMID 38890271, 2024). "Participants with high parasitemia had raised TNF‐α (p < .001), IFN‐ɣ (p < .001), IL‐1β (p < .001), IL‐6 (p < .001), GM‐CSF (p < .001), and IL‐10 (p < .001), but reduced IL‐3 (p < .001) and TGF‐β (p < .001) than those with low parasitemia." (PMID 39240033, 2024). "Both treatments were able to reduce parasitemia, reduce the amount of cardiac and intestinal cytokines, such as TNF- and IL-6, and increase the animals’ survival." (PMID 39598539, 2024). "The results showed that in the absence of IFN-γ, the concentration of MCP-1 increased ~10-fold, and IL-6 increased ~100-fold when compared to the C57BL/6 WT mice, suggesting that other cytokines are upregulated to try to control parasitemia." (PMID 37646522, 2023). "Animal studies have shown that parasitic infections increased the levels of pro-inflammatory cytokines (TNF-α, IFN-γ, and IL-6) and induced significant changes in the hemostatic system, suggesting a correlation between inflammation and clotting." (PMID 37063881, 2023). "The two doses of 103, or 102 of IL-6 Tg-PbANKA/LISP2 SPZ (group 2 and group 3, respectively) were inefficient at inducing sterile protection as challenged mice developed parasitemia at the same magnitude as the control mice, which received WT PbANKA SPZ only." (PMID 37143657, 2023). "Various clinical parameters, echocardiography findings, parasitemia status, brain natriuretic peptide (BNP) and troponin T (TnT) levels, and inflammatory biomarkers (IL-6, IL-10, IL-12p70, IL-17A, adiponectin, and IFN-γ) were assessed." (PMID 38109427, 2023). "Following infection, macrophages secrete inflammatory mediators such as IL-1β, IL-6, and TNF-α to control parasitemia." (PMID 36713380, 2022). "While some cytokines reached a maximum at peak parasitemia (IL-8, IL-10, KC-like) others rose only after the infection was treated (TNF, IL-6, MCP-1)." (PMID 34399690, 2021). "Serum levels of IL-6, IL-27, CCL3, CCL5, CXCL10, CCL11, and CCL17 in patients with different parasitic infection profiles living in the rural community of Brejo do Amparo, Januária, Minas Gerais, Brazil." (PMID 33777015, 2021). "Notably, multiple logistic regression analyses uncovered a negative association between parasitemia and the IL6 rs1800795 CG genotype (OR = 0.45, P = 0.015, 95% CI 0.24 −0.86) and a positive association between parasitemia and HIV infection (OR = 2.18, P = 0.039, 95% CI 1.04–4.58)." (PMID 33193300, 2020). "Collectively, IL-6, IL-18, IFN-γ, and IL-10 levels rose with parasitemia, while significant increases in IL-4 were biphasic, with a second peak occurring at day 10 p.i." (PMID 32958528, 2020). "These B cells responded differentially to parasite infection and a previous report supports this finding by showing that PerC B cells activated by anti-CD40 and LPS secreted more IL-10 and IL-6 compared to splenic B cells." (PMID 32197642, 2020).
parasitemia (continued). "Although the cytokines (IL-1β, IL-4, IL-6, IL-12, TNF-α, and IFN-γ) were increased in all groups after the parasite infection, the cytokine levels of the group immunized with SAG1-VLPs were markedly reduced compared to the non-immunized infection group." (PMID 32325746, 2020). "On the other hand, the reduced production of IFN-γ, IL-6, and TNF-α cytokines in C57BL/6 IL-17A knockout (IL-17A -/-) mice infected with T. cruzi Tulahuén strain produced a more severe parasitemia and mortality, than observed in wild-type mice." (PMID 33329529, 2020). "At the time of acute illness (day 1), subjects had upregulation of innate immune response, cytokine, and inflammation-related genes (IL-1β, IL-6, TNF, and IFN-γ), which was more frequent with parasitemias >100,000 per μL and body temperatures ≥39°C." (PMID 26491700, 2015). "Corroborating the critical role of TNF-α for host defense, Tc-TNF-R1−/− mice revealed increased parasitemia, accelerated death and more augmented TNF-α, IL-1 and IL-6 concentrations in circulation." (PMID 23717489, 2013). "We showed that adoptive transfer of highly enriched naïve CD4+CD25+ T cells (Tregs) led to increased peak parasitemia and production of disease exacerbating inflammatory cytokines, including IFN-γ, IL-6, TNF and MCP-1 early during infection in C57BL/6 mice." (PMID 22860150, 2012). "In Pk patients, there is also a direct correlation between age and angiopoietin-2 (a marker of endothelial activation), interleukin-6 (IL-6) (a pro-inflammatory cytokine), and microvascular dysfunction, independent of parasitemia." (PMID 37888606, 2023). "To test this possibility, we generated Mavs–/–Il6–/– DKO mice by crossing Mavs–/– mice with Il6–/‐ mice and found that the DKO mice generated strong immunity against N67C infections with lower parasitemia levels and markedly prolonged mouse survival compared to WT and Mavs–/– mice." (PMID 35635376, 2022). "IL-10 median levels were always lower in the case of STH regardless of age, whereas the level of IL-6 was reduced in individuals infected with filariae and intestinal parasitosis." (PMID 35421083, 2022). "The levels of IL-6 and IL-10 and the IL-10/TNF-α ratio were inversely associated with the age of the study participants in the absence of parasitic infections." (PMID 35421083, 2022). "Meta-regression analyses of continents, Plasmodium species, parasitemia, age groups, male percentage, characteristics of the control groups, and IL-6 measurement methods showed that these co-variates did not confound the effect estimate (P > 0.05)." (PMID 35396564, 2022). "Moreover, the depletion of the CD11b+Ly6Chi cells by the anti‐Ly6C antibody treatment at day three post YM infection markedly reduced the parasitemia levels and prolonged the survival of the WT mice that received early IFN‐α/β and late IL‐6 treatments." (PMID 35635376, 2022). "We also observed a negative correlation between TLR4, TLR5, TRIF, IL-6, IL-10, and IL-12p35 mRNA expression and parasitemia peak levels in infected mice." (PMID 34336720, 2021). "The production of pro-inflammatory cytokines (TNF-α, IL-1β, IL-6, and IFN-γ) in serum and brain homogenate of the vehicle-treated infected mice was significantly increased compared to the normal group on the peak day of parasitemia." (PMID 34975479, 2021). "Of note, the perturbation of the liver damage parameters ALT, AST, total bilirubin, and also MDP values of IL-4, IL-6, IL-8, IL-12p70, CXCL9, CCL5, CCL2, CRP, fibrinogen and parasitemia levels showed an inverse correlation with the time living in the endemic area." (PMID 34727121, 2021). "Furthermore, the immunization of SAG1-VLPs effectively decreased the production of specific cytokines, such as IL-1β, IL-6, TNF-α, and IFN-γ, after parasite infection." (PMID 32325746, 2020).
parasitemia (continued). "Taken together and despite the increase in IL-6 and MIF production by BeWo cells during parasite infection and under some oleoresin treatment conditions, in general, we observed that the oleoresin induced an anti-inflammatory profile to control parasite infection." (PMID 32938966, 2020). "The findings showed that major alterations occurred only at the acute parasitemia peak period (corresponding to 9 dpi) due to increased levels of IFN-gamma (5500-fold), TNF-alpha (754-fold) and IL-6 (260,000-fold) in untreated and infected mice as compared to uninfected and untreated animals." (PMID 30186314, 2018). "Correlation analysis demonstrates that despite the absence of correlation between IL-6 and parasitemia, a correlation between IL-10 and parasitemia levels was observed." (PMID 24741587, 2014). "Thus, massive phagocytosis of trypanosomes (as seen during peak parasitemia) leads to hyper-activation of macrophages and increased production of monokines (IL-1, TNF-α, IL-6, IL-12, monocyte chemotactic protein-1 [MCP-1]) and the T-cell cytokine (IFN-γ)." (PMID 23144931, 2012). "Also, increasing IL-6 levels mediates the production of acute-phase reactant proteins such as C-reactive proteins (CRP) and secretory phospholipase A2 (sPLA2) whereas moderate levels can reduce parasitemia." (PMID 33281757, 2020). "Higher levels of some pro-inflammatory mediators such as IL-6, MCP-1/CCL2 and IP-10/CXCL10 were observed in P. vivax-infected patients, which were re-established after anti-malarial treatment, suggesting that the parasite infection triggered an inflammatory response." (PMID 28118834, 2017). "Because IL6 is an acute inflammation protein and IL8 is involved in a long-term inflammatory process we further hypothesized that the exosomes secreted by T. vaginalis could potentially prime host cells for parasite infection." (PMID 23853596, 2013). "Additionally, the levels of IFN-γ and IL-6 were also higher in mice with elevated early IFN-Is than infections with low IFN-Is, suggesting that IFN-γ, IL-6 and other cytokines may contribute to the reduction of parasitemia and better host survival." (PMID 33344264, 2020). "In mothers of noninfected children, parasitemia showed a positive correlation with the levels of IL-12p70, IL-15, IFN-γ, and TNF-α and a negative correlation with IL-6." (PMID 38133693, 2023). "Patients with detectable parasitemia measured by RT-PCR in peripheral blood had a higher concentration of TNF-α, IL-1β, IL-4, and IL-6, whereas those with negative RT-PCR showed elevated levels of IL-17A." (PMID 38133693, 2023). "The deviation is exacerbated by the three mice that succumbed to parasitemia during the first peak and did not have the opportunity for Th2 type responses, mediated by IL10, IL13, IL4, and IL6 to develop." (PMID 35634275, 2022). "In these studies, IL-1β, IL-6, and TNF were upregulated more frequently in subjects with higher parasitemias and higher temperatures (data not shown)." (PMID 26491700, 2015). "JG single infected mice presented reduced parasitemia and heart parasitism, no mortality, levels of pro-inflammatory mediators (TNF-α, CCL2, IL-6 and IFN-γ) similar to those found among naïve animals and no clinical manifestations of disease." (PMID 20967289, 2010). "However, one study did not see a clear increase of TNF and IL-6 in asymptomatic parasitemia but, as expected, observed higher levels of TNF and IL-6 in individuals with acute malaria compared to those with asymptomatic infection." (PMID 40933276, 2025). "An animal study on dogs evaluating relationship of PCT with different inflammatory biomarkers (TNF-α, IL-1β, IL-6, and IFN-γ) produced during viral, bacterial, and parasitic infections showed that PCT showed a weak significant negative correlation with IFN-ꝩ levels in serum." (PMID 39343776, 2024).
parasitemia (continued). "Moreover, when the DT‐treated chimeric mice were pre‐treated with IFN‐α/β, they consistently showed parasitemia levels and survival similar to those of control groups (DT‐untreated chimeric mice with pretreatments of IFN‐α/β), suggesting that cDCs are not the main source of the late IL‐6 production." (PMID 35635376, 2022).
peritonitis (129 papers, 2007 to 2025). Inflammation of the peritoneum (tissue that lines the abdominal wall and covers most of the organs in the abdomen). "In our cohort, peritonitis, portal venous gas, and elevated levels of IL-6 and PCT were independently associated with the need for surgical intervention." (PMID 40464051, 2025). "This study identified peritonitis, portal venous gas, elevated IL-6, and elevated PCT as independent risk factors for early surgical intervention in neonates with NEC." (PMID 40464051, 2025). "Mainly, high IL-1β and IL-6 serum levels are associated with a high mortality risk in acute peritonitis." (PMID 39531431, 2024). "As expected, CLP-induced peritonitis was associated with strong systemic and local upregulation of pro-inflammatory cytokines IL-6, CCL2, and TNF as well as upregulation of anti-inflammatory IL-10 compared to sham animals." (PMID 38562925, 2024). "In the multivariate Cox regression analysis, after adjusting for DM, previous peritonitis episode and 24h urine volume, higher baseline dialysate IL-6 AR (HR 3.639, 95% CI 1.776–7.456, P = 0.002) were associated with an increased risk of UF insufficiency." (PMID 36035388, 2022). "Injecting LPS into the abdominal cavity of mice can cause peritonitis and a significant increase in cytokines in mice, including IL-6, IFN-γ, IL-1β, nitric oxide (NO), and TNF-α." (PMID 34884814, 2021). "As expected, CLP-induced peritonitis was associated with a strong local and systemic up-regulation of the pro-inflammatory cytokines IL-6, MCP-1, and TNFα in WT mice." (PMID 33362762, 2020). "IL-6 was also evaluated for comparative purposes as the hallmark cytokine in inflammatory processes and in PD-associated peritonitis." (PMID 29850544, 2018). "In patients with GI perforation, peritonitis and septic shock rapidly progress due to the significant number of Gram-negative bacilli from bowel spillage, which in turn causes the release of inflammatory cytokines such as interleukin-1 and interleukin-6." (PMID 35264127, 2022). "Apart from increased splenic Il6 expression, other systemic or local inflammatory readouts determined in blood, spleen, and peritoneum were unaltered in myeloid-specific Acly-deficient mice during endotoxin-induced peritonitis in vivo." (PMID 33981315, 2021). "Compared with monomicrobial peritonitis, polymicrobial peritonitis is associated with increased proinflammatory cytokines such as IL-6, keratinocyte chemoattractant, macrophage inflammatory protein-1α, monocyte chemoattractant protein-1, and granulocyte colony-stimulating factor." (PMID 28666415, 2017). "Also, given the cause-and-effect relationship between peritonitis and IL-6 levels, a sensitivity analysis including only peritonitis-free patients was performed to confirm the robustness of the findings." (PMID 24410736, 2014). "In addition, when PSTR was re-examined in those free of peritonitis, a consistent association with dialysate IL-6 levels was observed." (PMID 24410736, 2014). "Oral administration of LPE has been shown to attenuate peritonitis by reducing pro-inflammatory mediators (IL-1β, IL-6, and TNF-α) and increasing IL-10 secretion." (PMID 40079578, 2025). "Previous studies have shown that BjV causes leukocyte infiltration with the predominance of neutrophils in mice muscle tissue, neutrophil migration in peritonitis, and increased levels of IL-6 and IL-1β in the peritoneal cavity." (PMID 40864043, 2025). "Second, macrophage TET2 expression is essential for antibacterial responses, protecting against conditions like peritonitis and abdominal sepsis, partly by inhibiting proinflammatory cytokines such as IL-6." (PMID 40794443, 2025). "Multivariate logistic regression identified peritonitis (OR = 95.635), IL-6 (OR = 1.001), and portal venous gas (OR = 22.551) as independent risk factors for early surgery in NEC (P < 0.05)." (PMID 40464051, 2025).
peritonitis (continued). "In a mouse model of LPS-induced peritonitis, treatment with Rhy significantly reduced serum levels of IL-6, TNF-α, and NO." (PMID 41031160, 2025). "Our results revealed that baicalin can decrease the protein expressions of TNF-α, IL-1β, and IL-6 in GPS-infected PPMCs and piglets, which suggests that the regulation of inflammatory injury is helpful in alleviating peritonitis caused by GPS." (PMID 40867785, 2025). "Previous research has demonstrated that increased TMAO induces the production of IL-6 and TNF-α, exacerbating peritoneal inflammation in peritoneal dialysis patients and increasing the risk of peritonitis." (PMID 38500584, 2024). "We evaluated in vivo eryptosis percentage in blood fresh samples and pWBC, pNGAL, and peritoneal cytokines (IL-1 β and IL-6), as specific peritoneal markers of peritonitis." (PMID 38673869, 2024). "DW18134 significantly reduced the LPS-stimulated expression of Tnfa, Il6, and Il1b in peritonitis mice livers; the effect showed good dose dependence at 15 mg/kg and 30 mg/kg." (PMID 38675622, 2024). "IL-6 is also considered an important cytokine in peritoneal fibrosis, leading to peritonitis and fibrosis development through the STAT3-dependent pathway." (PMID 38483736, 2024). "In combination with visible peritonitis after the induction of surgery and reproducibly high IL6, IL-10 and TNF-alpha levels in previous studies with the same model, an abdominal infection of the animals is reliably detected." (PMID 39273258, 2024). "Peritonitis promotes peritoneal fibrosis through inflammatory factors such as IL-1β and IL-6, exacerbating the chronic induction of TGF-β1 synthesis, and promoting fibrosis events." (PMID 37817984, 2023). "Pro-inflammatory cytokines were elevated after 24 h of peritonitis formation, especially IL-1Ra, IL-1b, IL-6, IL-8, and TNF-α." (PMID 38087374, 2023). "We evaluated eryptosis percentage, CRP, IL-6, and IL-1β levels in the PD controls and in the PD patients with peritonitis on the first day of peritonitis." (PMID 36498493, 2022). "A retrospective observational study included 31 PD patients had reported that patients who developed peritonitis had higher baseline dialysate IL-6 level (58.4 ± 12.6 vs. 20.3 ± 8.7 pg/mL, p = 0.07) than that in patients who remained peritonitis-free." (PMID 36035388, 2022). "Several studies have found that intraperitoneal IL-6 levels are increased before and during peritonitis and remain high level even several months after clinical cure of peritonitis." (PMID 36035388, 2022). "Our results showed that TAK 242 significantly inhibited the production of inflammatory cytokines in the peritoneal lavage fluid of mice with peritonitis, including IL-6, IFN-γ, IL-1β, NO, and TNF-α." (PMID 34884814, 2021). "The number of peritonitis episode during follow up period also significantly correlated with the PD effluent IL-6 (r = 0.305, p = 0.047) and COX-2 levels (r = 0.374, p = 0.016) after one year." (PMID 32296091, 2020). "Initial recruitment of neutrophils and IL-6 secretion during acute peritonitis was described to be dependent on IFNγ." (PMID 31694340, 2019). "Early production of CCL3, as well as CCL2 and cytokines such as IL-1β, IL-6, IL-12, and IL-1Ra, was observed in an acute antigen-induced peritonitis model, showing that peritoneal-resident cells are an important source of these mediators." (PMID 30937315, 2019). "IL-6−/− mice were protected from the development of fibrosis in recurrent inflammatory activation of peritonitis." (PMID 31694340, 2019). "T cell recruitment was impaired in IL-6−/− mice in a mouse model of peritonitis due to reduced chemokine expression which was mediated by STAT3 activation." (PMID 31694340, 2019). "Studies in peritonitis models suggest that IL-6 signaling is of crucial importance in the transition from the acute to the chronic phases of inflammatory processes." (PMID 29443928, 2018).